FTO (FTO alpha-ketoglutarate dependent dioxygenase)
Diseases named in the same sentence as FTO in open-access papers (continued):
Sharing a sentence is not in itself a finding about the gene and the disease.
breast tumor (11 papers, 2019 to 2026). "Our results showed that samples with higher FTO expression (vs average expression level of FTO in breast tumor tissues) was frequently associated with lower BNIP3 level and vice versa." (PMID 30922314, 2019). "We observed that loss of FTO effectively inhibited breast tumor growth in mice as reflected by the significant reduction of tumor size and tumor weight comparing to the controls." (PMID 30922314, 2019). "Our findings not only highlight the diagnostic complexity of this rare breast neoplasm, which is prone to misclassification, but also expand the known genetic landscape of PA through the discovery of the novel PLAG1::FTO fusion." (PMID 41869656, 2026). "Our results showed that double knockout cells significantly alleviated the inhibitory effects on tumor growth mediated by FTO deficit, proving that FTO promoted breast tumor growth primarily via modulating BNIP3 expression by the m6A modification." (PMID 30922314, 2019). "To validate their correlation, we performed the immunohistochemistry assay to detect the protein levels of BNIP3 and FTO in our breast tumor sample cohort consisting of 36 primary breast tumor tissues." (PMID 30922314, 2019). "By analyzing the data set (GSE9014), we detected the levels of BNIP3 and FTO in normal and breast tumor samples." (PMID 30922314, 2019). "Taken together, our results indicated that FTO plays a critical role in promoting breast tumor growth and metastasis in vivo." (PMID 30922314, 2019). "c Immunohistochemistry (IHC) of human normal breast (12 samples) and breast tumor (36 samples) tissues with a specific antibody against FTO." (PMID 30922314, 2019). "To validate the up-regulated RNA level of FTO, we performed the immunohistochemistry (IHC) staining assay to detect the protein expression level of FTO in 36 clinical human breast tumor tissues and 12 corresponding NT adjunct breast tissues." (PMID 30922314, 2019). "Double knockdown of BNIP3 and FTO promoted breast tumor growth in mice as reflected by the significant increase of tumor size and tumor weight comparing to the stable FTO-knockdown cells." (PMID 30922314, 2019). "Treatment with Rhein, a FTO inhibitor, decreased tumorigenesis in mice bearing breast tumors." (PMID 30922314, 2019). "Similarly, senescent TINs-derived exosomes could also promote the EMT and activate FTO/ZEB1 signaling in breast tumor cells." (PMID 36302751, 2022). "Furthermore, western blot revealed that the protein levels of METTL3, METTL14, and FTO were significantly lower in seven breast tumor samples randomly selected from RT-qPCR samples, while YTHDF1 and YTHDF3 had higher protein expression compared to adjacent tissues." (PMID 34804948, 2021). "FTO mediated the m6A demethylation of BNIP3 mRNA and induced its degradation, thus promoting breast tumor progression." (PMID 38782769, 2024). "A significant negative correlation between BNIP3 and FTO levels was observed in breast tumors (coefficient = − 0.3083, P = 0.0029)." (PMID 30922314, 2019).
mental disorder (11 papers, 2016 to 2025). A disease that has its basis in the disruption of mental process. "In other psychiatric disorders, the genetic variation of FTO was also shown to contribute to the risk of other psychiatric disorders, including Alzheimer’s disease." (PMID 37047192, 2023). "Nevertheless, the link between variants in FTO and mental disorders has been barely explored." (PMID 31033179, 2019). "Their results suggested that this FTO variant was associated with common mental disorders in men, but not in women." (PMID 35308733, 2022). "Considering the regulatory role of FTO in learning and memory, we speculate that FTO might play an important role in normal cognitive function and psychiatric diseases by regulating dopaminergic function through mRNA methylation modification." (PMID 35528183, 2022). "Our study extends the well-documented role of the FTO gene in metabolic traits to include psychiatric traits, suggesting a broader functional role for FTO which could have implications for understanding the genetic basis of psychiatric disorders." (PMID 39080362, 2024).
rheumatoid arthritis (11 papers, 2020 to 2025). A chronic, systemic autoimmune disorder characterized by inflammation in the synovial membranes and articular surfaces. "In the context of rheumatoid arthritis (RA), increased expression of m6A writer proteins and reduced expression of m6A eraser proteins fat mass and obesity -associated protein (FTO) and AlkB homolog 5 (ALKBH5) have been reported to correlate with disease severity." (PMID 41009809, 2025). "Moreover, some studies found that polymorphisms of METTL3 and fat mass and obesity associated (FTO) genes are involved in the pathogenesis of some autoimmune diseases, such as rheumatoid arthritis (RA) and latent autoimmune diabetes (LADA)." (PMID 34616359, 2021). "In rheumatoid arthritis, FTO knockdown or inhibition significantly reduces the severity of arthritis." (PMID 39980685, 2025). "Compared with FTO, there is less research on SMIM21, but epidemiological studies have also found its significant association with rheumatoid arthritis." (PMID 35222278, 2022). "For example, FTO, ALKBH5 and YTHDF2 have been described as risk factors for rheumatoid arthritis." (PMID 41009809, 2025). "For example, global m6A and METTL3 expression levels have been shown to be significantly increased, while FTO, ALKBH5 and YTHDF2 mRNA levels have been shown to be significantly downregulated in rheumatoid arthritis (RA)." (PMID 36457997, 2022). "Likewise, m6A levels in rheumatoid arthritis (RA) patients’ and ischemic stroke patients’ blood were elevated relative to healthy controls, along with decreased ‘eraser’ ALKBH5 and FTO levels and increased YTHDF2 ‘reader’ levels in RA samples." (PMID 36831575, 2023). "However, little is known about the role of ALKBH5, FTO, and YTHDF2 in rheumatoid arthritis (RA)." (PMID 32884942, 2020).
diabetic retinopathy (10 papers, 2018 to 2025). "The rs9939609 polymorphism in the FTO gene is strongly associated with an increased risk of diabetic retinopathy (DR) in patients with type 1 diabetes (T1D)." (PMID 41315216, 2025). "The fat mass and obesity-associated (FTO) protein, an N6-methyladenosine (m6A) demethylase, influences endothelial cell (EC) function and retinal homeostasis in diabetic retinopathy (DR), thus providing a promising nanotherapeutic approach for DR." (PMID 38297099, 2024). "Our murine studies proved a causative role of FTO in retinal ECs, as shown by EC FtoΔ/Δ mice, which were protected against severe diabetic retinopathy, and we additionally linked FTO to inflammation alterations." (PMID 37781923, 2023). "FTO polymorphism was also linked to a higher risk of diabetic retinopathy." (PMID 39744011, 2024). "In diabetic retinopathy, recent studies have demonstrated that FTO expression is upregulated in endothelial cells under diabetic conditions." (PMID 41315216, 2025). "H3K18la aggravates diabetic retinopathy microvascular abnormalities by promoting the expression of the m6A eraser FTO." (PMID 41199784, 2025). "FTO showed a pro-angiogenic role in diabetic retinopathy, but an anti-angiogenic role in intrahepatic cholangiocarcinoma." (PMID 36291060, 2022). "The findings revealed that miR-192 delayed the damage to RPE cells triggered by HG treatment by targeting FTO, which improved diabetic retinopathy therapy." (PMID 35441575, 2022). "After stratification of patients according to the presence/absence of vascular complications, we found significant associations of variants in the CAT, FTO, and UCP1 genes with diabetic retinopathy and nephropathy." (PMID 29410390, 2018). "The regulation of FTO plays a critical role in the progression of diabetic retinopathy (DR)." (PMID 41315216, 2025). "To confirm the sequencing findings, we proved that the protein level of TNIP1 was decreased, accompanied by upregulated FTO, in the retinal fibrovascular membranes of the patients with diabetic retinopathy, diabetic murine retinas, and HRMECs treated with high glucose." (PMID 37781923, 2023). "FTO expression was elevated in diabetic mice retinas and systemic administration of FTO inhibitor FB23-2 exhibited therapeutic efficacy in mice with diabetic retinopathy." (PMID 39744011, 2024).
esophageal cancer (10 papers, 2021 to 2025). A primary or metastatic malignant neoplasm involving the esophagus. "Increased expression of FTO in esophageal cancer tissues is associated with poor clinical prognosis." (PMID 40823087, 2025). "The results showed that downregulation of FTO was correlated with increased expression of E-cadherin (E-cad) in KYSE150 cells, indicating that FTO might be associated with E-cadherin-regulated cell migration in esophageal cancer cells." (PMID 38491196, 2024). "We found that m6A demethylase fat mass and obesity-associated protein (FTO) was highly expressed in esophageal cancer (EC) stem-like cells, and that its level was also substantially increased in EC tissues, which was closely correlated with a poor prognosis in EC patients." (PMID 35568876, 2022). "To further identify whether FTO expression is associated with esophageal cancer histology, we analyzed The Cancer Genome Atlas (TCGA) data through the UALCAN database and found that FTO expression was significantly upregulated in 95 ESCC specimens compared to 11 normal esophageal epithelial cells." (PMID 35524932, 2022). "Compound C6 targets FTO to display anti-tumor activity against esophageal cancer via the inhibition of the EMT pathway." (PMID 40823087, 2025). "We found that the m6A demethylase FTO was significantly upregulated in esophageal cancer cell lines and patient tissues." (PMID 38491196, 2024). "Previous studies have shown that FTO plays a carcinogenic role in esophageal cancer and other solid tumors." (PMID 38491196, 2024). "By using transcriptome-wide m6A-seq and RNA-seq assays, we revealed that AKT3 is a downstream target of FTO and acts in concert to regulate the tumorigenesis and metastasis of esophageal cancer." (PMID 38491196, 2024). "To investigate the potential roles of FTO in esophageal cancer cells, we performed a series of functional assays to characterize the effect of FTO." (PMID 38491196, 2024). "Based on these results, we investigated the correlation between the combined effect of FTO and multiple m6A regulatory proteins and the prognosis of esophageal cancer patients and found that an increase in the FTO/METTL14 ratio can lead to poor prognosis." (PMID 38491196, 2024). "In contrast, METTL14 knockdown had the opposite effect: METTL14 knockdown increased the migration or invasion of KYSE150 cells, but the effects of METTL14 on esophageal cancer cell phenotype induced by FTO between the two." (PMID 38491196, 2024). "Analysis of esophageal cancer patients with higher FTO/METTL14 ratios revealed poorer prognoses than patients with lower FTO/METTL14 ratios." (PMID 38491196, 2024). "Our results describe the roles of m6Aand FTO in cancer progression and provide a basis for the development of therapeutic strategies against esophageal cancer metastasis." (PMID 38491196, 2024). "Experiments have shown that FTO is significantly upregulated in esophageal cancer cell lines and patient tissues." (PMID 38491196, 2024). "All these results indicated that the oncogenic role of FTO is involved in cell proliferation, migration, invasion, and cell apoptosis in esophageal cancer cells." (PMID 38491196, 2024). "In vivo and in vitro assays demonstrated that FTO was involved in the proliferation and apoptosis of esophageal cancer cells." (PMID 38491196, 2024). "Recent report demonstrated that esophageal cancer tissues had the increased FTO expression which correlated with clinical esophageal cancer prognosis." (PMID 35833378, 2022). "Data from the GEPIA database showed that FTO was significantly upregulated in 182 esophageal cancer tissue samples compared to 286 normal esophageal epithelial tissue samples." (PMID 35524932, 2022). "Fat mass and obesity-associated protein (FTO), a demethylase for N6-methyladenosine modification, has been implicated in esophageal cancer." (PMID 35833378, 2022).
esophageal cancer (continued). "Additionally, METTL3, FTO, ALKBH5, and IGF2BP2 are overexpressed in patients with esophageal cancer and closely linked to myc mRNA expression." (PMID 39791162, 2025). "FTO plays an oncogenic role in esophageal cancer, promoting cell proliferation and migration." (PMID 40823087, 2025). "Subsequent functional studies revealed an oncogenic role of FTO in esophageal cancer tumorigenesis." (PMID 38491196, 2024). "However, during the development of esophageal cancer, FTO has an antagonistic effect on the expression of METTL14, and this effect is related to the ratio of FTO to ALKBH5." (PMID 38491196, 2024). "Moreover, we found that the m6A methyltransferase METTL14 negatively regulates FTO function in esophageal cancer progression." (PMID 38491196, 2024). "We found a significantly upregulated level of FTO in esophageal cancer cells." (PMID 38491196, 2024). "Notably, the METTL14/FTO/AKT3 signaling network might have other normal functions in addition to influencing tumorigenesis in esophageal cancer." (PMID 38491196, 2024). "Therefore, FTO might be a potential therapeutic target in esophageal cancer, and compound C6 could be a promising candidate for the drug discovery to treat esophageal cancer." (PMID 35833378, 2022). "In addition, FTO could play oncogenic roles and promote cell proliferation and migration in esophageal cancer." (PMID 35833378, 2022). "Therefore, FTO might be a potential target and FTO inhibitors might be effective and novel anticancer agents for the treatment of esophageal cancer." (PMID 35833378, 2022). "Meanwhile, the FTO/YTHDF2 axis controls the downregulation of LINC00022, thereby influencing proliferation and tumor growth in esophageal cancer." (PMID 39791162, 2025). "We found that the m6A methyltransferase METTL14 is also involved in FTO-regulated m6A modification and acts in concert with FTO to regulate AKT3 methylation in the tumorigenesis and metastasis of esophageal cancer." (PMID 38491196, 2024). "To further investigate the correlation between FTO and AKT3 in esophageal cancer tumorigenesis, we overexpressed AKT3 in KYSE150 cells and performed an additional FTO knockdown." (PMID 38491196, 2024). "To test the potential role of FTO and AKT3 in esophageal cancer biogenesis in vivo, we injected sh-FTO- or AKT3-overexpressing KYSE150 cells subcutaneously into nude mice." (PMID 38491196, 2024). "In this work, compound C6 was identified as a novel FTO inhibitor and regulated EMT pathway and PI3K/AKT pathway against esophageal cancer." (PMID 35833378, 2022). "Then, ELISA result showed that METTL3 and METTL14 were highly expressed in esophageal cancer, whereas FTO and ALKBH5 expressed lowly in esophageal cancer." (PMID 33596916, 2021). "FTO alone is not related to the prognosis of esophageal cancer, and its function is antagonized by METTL14." (PMID 38491196, 2024). "Our research showed that the independent expression of FTO was not significantly correlated with the prognosis of esophageal cancer patients, which is different from the mechanism of ALKBH5." (PMID 38491196, 2024). "Moreover, we found that the m6A methyltransferase METTL14 is also involved in FTO-regulated m6A modification and acts in concert with FTO to regulate AKT3 methylation in the tumorigenesis and metastasis of esophageal cancer." (PMID 38491196, 2024). "Furthermore, our study indicated that although METTL3, METTL14, FTO and ALKHB5 differentially expressed in esophageal cancer patients’ tissues and normal esophageal tissues, only METTL3 expression was related to esophageal cancer recurrence." (PMID 33596916, 2021). "Importantly, we revealed that FTO operates through a regulatory network of m6A modifications that involves METTL14, YTHDF1 and AKT3 signaling, providing the first insight into the mechanism of FTO-mediated esophageal cancer progression." (PMID 38491196, 2024).
esophageal cancer (continued). "We found that downregulation of FTO or overexpression of METTL14 had similar effects on multiple aspects of esophageal cancer progression, including migration, invasion, proliferation, and tumorigenesis, which also suggested that FTO function could be restored by METTL14 in esophageal cancer." (PMID 38491196, 2024).
hyperlipidemia (10 papers, 2012 to 2023). "In contrast to its beneficial role in ischemic HF (discussed later), upregulated FTO has been described as detrimental in hyperlipidemia-induced cardiomyopathy." (PMID 35991314, 2022). "Therefore, it is reasonable to assume that FTO regulates the stability of CD36 mRNA via YTHDF2 dependent on the m6A modification in hyperlipidemia and PA-induced cardiomyocyte inflammation." (PMID 34881240, 2021). "Likewise, we showed that the chemically modified monomeric compound LHD could bind to FTO and interfere with the FTO-mediated m6A modification, thereby ameliorating the hyperlipidemia- and PA-induced inflammatory responses in cardiomyocytes." (PMID 34881240, 2021). "However, it has not been confirmed if FTO is a promising target for the treatment of hyperlipidemia-induced cardiomyocyte inflammation." (PMID 34881240, 2021).
nasopharyngeal carcinoma (10 papers, 2023 to 2025). A carcinoma arising from the nasopharyngeal epithelium. "In nasopharyngeal carcinoma, FTO enhanced radiotherapy resistance through repressing the radiation-induced ferroptosis." (PMID 40712780, 2025). "Upregulation of FTO in radioresistant nasopharyngeal carcinoma (NPC) tissues and cells, relative to their parental radiosensitive parts, was also observed." (PMID 41369374, 2025). "For instance, as an m6A demethylase, FTO inhibits radiation-induced ferroptosis, thereby enhancing the radioresistance of nasopharyngeal carcinoma (NPC) cells." (PMID 40271153, 2025). "It was reported that FTO is significantly upregulated in radioresistant nasopharyngeal carcinoma (NPC) tissues." (PMID 38473842, 2024). "In nasopharyngeal carcinoma radiotherapy, the demethyltransferase FTO promotes the expression of deubiquitylase (OTUB1) expression to counter ferroptosis and bolster the nasopharyngeal carcinoma radioresistance." (PMID 38473842, 2024). "Similarly, high levels of the m6A demethylase FTO correlate with poor prognosis in nasopharyngeal carcinoma (NPC), and silencing FTO can effectively halt NPC growth and metastasis." (PMID 40271153, 2025). "This study is the first to explore the malignant biological effects of the combined action of demethylase FTO and ALKBH5 in nasopharyngeal carcinoma." (PMID 38263362, 2024).